TJP1 (tight junction protein 1)
Diseases named in the same sentence as TJP1 in open-access papers (continued):
Sharing a sentence is not in itself a finding about the gene and the disease.
invasive ductal carcinoma (1 paper, 2020). "For validation, the feature and spatial feature plots of MAF, CD248, GJA1, LAMA3, TJP1, LAMC2, and COL17A1 demonstrated to show the location in BRCA samples, and they were highly-expressed in the invasive ductal carcinoma tissue (cluster 2, 4, 7, 9, 12)." (PMID 33585235, 2020).
kidney cancer (1 paper, 2023). Primary or metastatic malignant neoplasm involving the kidney. "As KIRC accounts for 80% of all kidney cancers, we next focused on investigating the function and mechanism of TJP1 in KIRC." (PMID 37790849, 2023).
neovascular glaucoma (1 paper, 2024). "Diseases associated with TJP1 include neovascular glaucoma and brain oedema and TJP1 related pathways include G-Beta gamma signalling and E-cadherin signalling in the nascent adherens junction." (PMID 38892455, 2024).
scleroderma (1 paper, 2022). Scleroderma is a rare autoimmune connective tissue disorder characterized by abnormal hardening of the skin and, sometimes, other organs. "However, mesenchymal–epithelial transition (MET) associated proteins such as SCRIB, DSP, TJP1, CDH1, DLG1, and TJP2 were downregulated in scleroderma skin, indicating the high severity of skin fibrosis in mice with scleroderma." (PMID 35315234, 2022).
Ventricular arrhythmia (1 paper, 2024). "The concomitant Cx43—Nav1.5 interaction and their translational relevance was previously shown in a study which lead to a significant loss of Nav1.5 and severe ventricular arrhythmia after deletion of the last five amino acids of Cx43 – representing a binding motif for tight-junction-protein-1." (PMID 39382673, 2024).
infection (274 papers, 2008 to 2026). The state of being infected such as from the introduction of a foreign agent such as serum, vaccine, antigenic substance or organism. "The mRNA expression of TJP1, TJP2, and ZO-1, which are associated with the intestinal permeability barrier, were affected by the PAstV1 infection." (PMID 31847270, 2019). "In addition, the mRNA expression of the tight junction protein 1 and 2 and zonula occludin 1, which are associated with the intestinal barrier permeability, were affected after PAstV1 infection." (PMID 31847270, 2019). "Interestingly, the mRNA expression of TJP1 and ZO-1, which are associated with intestinal permeability, were significantly decreased after PAstV infection, suggesting that intestinal damage induced by the virus was related to an increase in the intestinal permeability barrier." (PMID 31847270, 2019). "At 72 hours post-infection, there was a significant decrease in mRNA transcription levels of TJ proteins (Tight Junction Protein 1, occludins, and claudin-5) compared to control cells." (PMID 40584180, 2025). "Western blot analysis showed that infection with H. pylori also led to increases in Zona occludens 1(ZO1, Human homologue to Tjp1) protein expression in vitro in MKN28 gastric epithelial cells, and that this increase was inhibited in the presence of NS398." (PMID 19317916, 2009). "This infection contributes to the dysfunction of the blood–brain barrier endothelium, likely through the degradation of intercellular contacts, particularly tight junction protein 1 (ZO-1)." (PMID 39203574, 2024). "Interestingly, expression of TJP1, F11R, OCLN and CLDN5 were transiently increased after 2 or 4 days of infection before their downregulation (median increase up to 28.4% for TJP1, 33.5% for F11R, 110.4% for OCLN and 51.6% for CLDN5)." (PMID 37537664, 2023). "Moreover, in this intranasal infection model, increased mRNA levels of Cdh1 (E-cadherin), Tjp1 (ZO-1), Cldn4 (claudin 4), Cldn5 (claudin 5), and Cldn18 (claudin 18) were observed after IFN-β treatment." (PMID 36559113, 2022). "Interestingly, expression of OCLN was increased in hCMEC/D3s with infection, and we observed a tendency towards upregulation of TJP1 and CLDN5 together with downregulation of SNAI1 after 8 h of N. meningitidis infection." (PMID 36289516, 2022). "We also detected a discrete reduction of ZO-1 (encoded by Tjp1) expression upon infection, without change and in the levels of Claudin-2 and Claudin-11." (PMID 35027063, 2022). "In addition, the infection of CFBE41o- cells with B. contaminans decreases tight junction protein 1, ZO-1, and claudin-1, as well as occludin and indicated that tight junction degradation occurs via a decrease in numerous protein components." (PMID 26636042, 2015). "We found the mRNA transcription levels of TJP1, OCLN, and CLDN5 were unaffected by the infection at 24 h, but were significantly decreased after 72 h of SARS-CoV-2 infection." (PMID 35705998, 2022). "In order to track changes in tissue expression of tight junction proteins in gill epithelia of carp under infection with CEV, immunohistochemistry staining for tight junction protein-1 (ZO-1) was performed." (PMID 34269137, 2021). "More importantly, colonic expression of both Ocln and Tjp1 was significantly higher in these mice, pointing out the detrimental role of IL-33/ST2 signaling on gut epithelium integrity during CR infection." (PMID 33654214, 2021). "On the other hand, knockdown of CLDN1, TJP1, CD63, 14-3-3 β, and GLUT4 reduced HCV RNA level more than 50% at 12 hrs post infection." (PMID 23593195, 2013). "To further rule out that the expression of tight junction proteins is not altered in response to infection, we conducted qPCR to assess the expression of the tight junction proteins ZO-1 (TJP1) and occludin (OCLN)." (PMID 38756230, 2024).
infection (continued). "Eta variant at MOI 1 also transiently induced an increase in tight and adherens junction expression at 2 dpi (median increase for TJP1: 33.5%; F11R: 38.3%; OCLN: 25.9%; CLDN5: 96.6% and CDH5: 74.5%) before expression levels returned to the uninfected condition ones after 6 days of infection." (PMID 37537664, 2023). "However, among the infected mice, this downregulation was also present in the infection+nisin group, and was not prevented by treatment with nisin, although some positive trends were noted for Tjp1/ZO-1." (PMID 38233485, 2024). "In addition, infection with whole Gram-negative bacteria revealed a significant increase in all analysed TJ proteins in Alpk1−/− organoids, while RNA expression levels of Tjp1 and Cldn8 were decreased." (PMID 32076438, 2020). "Importantly, siRNA-mediated knockdown of TJP1, CD63, 14-3-3 β, SUMO1 or GLUT4 reduced the infectivity of HCV by more than 50%, whereas knocking down either of the other two proteins (integrin β1 and CASK) did not affect infection of HCV JFH1 5A-Rluc." (PMID 23593195, 2013).
tumor (229 papers, 2006 to 2025). "Tight junction protein 1 (TJP1) is considered a tumor suppressor, and its downregulation has been associated with invasive features of cancer." (PMID 37693069, 2023). "We performed similar analysis for two other genes known to be relevant to tumor grade in CRC: the tight junction-associated protein ZO-1/TJP1, and a regulator of epithelial-mesenchymal transition, TGFβ1." (PMID 34237057, 2021). "Additionally, TJP-1 has been reported to be involved in epithelial–mesenchymal transition (EMT) processes associated with tumor invasion." (PMID 38255907, 2024). "Therefore, TJP-1 is believed to play a significant role in the processes underlying tumor growth, and its expression is closely associated with patient prognosis." (PMID 38255907, 2024). "Moreover, low TJP1 expression was significant associated with higher tumor grade and pathologic stage, indicating TJP1 is a favorable prognostic marker in KIRC." (PMID 37790849, 2023). "Another study reported that TJP1, whose expression is low in MM, inhibits tumor metastasis by increasing the adhesion of MM cells to bone marrow stroma." (PMID 40173324, 2025). "These exosomes regulate target genes such as phosphatase and tensin homolog (PTEN) and tight junction protein 1 (TJP1) expression, and stimulate tumor cells to secrete more growth factors and chemokines, thereby promoting the malignant progression of tumors." (PMID 39497820, 2024). "In some instances, Tjp1 has been found to regulate key signaling pathways involved in tumor growth and survival, such as the Akt and ERK pathways." (PMID 38255907, 2024). "TJP1 also promotes angiogenesis in tumor progression by moving from the membrane to the cytoplasm in A549 cells after TGF-β treatment." (PMID 38994952, 2024). "TJP1 overexpression significantly suppressed cell proliferation and tumor growth in 786-O cells, whereas the addition of an autophagy inhibitor diminished its inhibitory function." (PMID 37790849, 2023). "In our study, we observed a significant correlation between low TJP1 expression and tumor grade as well as poor prognosis in KIRC." (PMID 37790849, 2023). "Taken together, these results suggest that TJP1 serves as a favorable prognostic marker and induces autophagy to suppress cell proliferation and tumor growth in KIRC." (PMID 37790849, 2023). "Further analysis revealed that low TJP1 expression also correlated with poor overall survival in KIRC patients with same tumor grade." (PMID 37790849, 2023). "Our experiments revealed that TJP1 inhibited cell proliferation and tumor growth by inducing the autophagy process." (PMID 37790849, 2023). "The results demonstrated a correlation between decreased TJP1 expression, advanced tumor stage and poorer overall survival in KIRC." (PMID 37790849, 2023). "TJP1, an adaptor protein of the adhesive barrier, has been found to exhibit distinct oncogenic or tumor suppressor functions in a cell-type dependent manner." (PMID 37790849, 2023). "The function of TJP1 in tumor cell and inflammatory cell communication will be a spot worth studying in the future." (PMID 37790849, 2023). "Mice injected with 786-O cells stably expressing TJP1 showed decreased tumor volume and weight compared to control group and mice treated with 3-MA." (PMID 37790849, 2023). "We first analyzed TJP1 expression in the TCGA database, considering clinical tumor stage and overall patient survival." (PMID 37790849, 2023). "Firstly, it provides the first evidence of the involvement of TJP1 in regulating autophagy and its impact on tumor behavior in KIRC." (PMID 37790849, 2023). "Accumulating evidence have suggested that TJP1 plays a key role in cancer development and progression, such as tumor vascular normalization, tumor chemoresistance and effective mucosal repair." (PMID 37790849, 2023). "Other tight junction proteins, such as tight junction protein 1 (TJP1) and Claudin‐5, have been indicated to regulate vascular abnormalities during tumour progression." (PMID 35224833, 2022).
tumor (continued). "Ni and colleagues found that the expression of TJP1 was decreased in NSCLC tissue in comparison to adjacent non-tumour tissue and its overexpression was correlated with better prognosis in NSCLC patients." (PMID 29062084, 2017). "During EMT, tumor cells gradually lose the epithelial markers (E-cadherin, tight junction protein-1, laminin and cytokeratin) and obtain the expression of mesenchymal markers (N-cadherin, Vimentin and α–SMA)." (PMID 28938653, 2017). "The tight junction protein 1 (claudin-1) is an important inhibition protein of tumor infiltration function." (PMID 24758579, 2014). "The mean tumor size was 16.1 mm (95% CI_ 13.84 to 20.33 mm) for mice injected with Tjp1 KO B16-F10 cells and 14.9 mm (95% CI_ 9.71 to 18.56 mm) for mice injected with Tjp1 re-expressed B16-F10 cells." (PMID 38255907, 2024). "After comparing the mean tumor sizes of all treatment groups, we discovered that tumor growth was significantly increased in the Tjp1 and Tjp2 KO injected groups and growth rates recovered in the Tjp1 and Tjp2 re-expressing groups." (PMID 38255907, 2024). "In summary, tumorigenic characteristics, including cell proliferation, migration, invasion, tumor growth, and metastatic potential, were significantly increased in Tjp1 and Tjp2 KO cells, and the knockout of Tjp genes significantly affected the expression of related proteins." (PMID 38255907, 2024). "Additionally, we analyzed the effects of Tjp1 and Tjp2 KO on tumor growth and experimental metastasis in an in vivo model." (PMID 38255907, 2024). "While TJP1 expression in tumour cells is repressed in activated EMT, we found that the expression levels of SNAI2 and TWIST1 were significantly decreased in Ex-MaPac107 and the expression of ZEB1 was significantly increased in Ex-MaPac107 compared with Pri-MaPac107." (PMID 37686338, 2023). "In a xenograft model of KIRC, overexpressing TJP1 dramatically attenuated tumor proliferation, which could be restrained by 3-MA injection." (PMID 37790849, 2023). "Additionally, our research demonstrated that the overexpression of TJP1 induced autophagy signaling, resulting in the inhibition of cell proliferation and tumor growth in both KIRC cells and xenograft models." (PMID 37790849, 2023). "Collectively, these findings suggest that TJP1 suppresses cell proliferation and tumor growth by inducing autophagy in KIRC cells, which could serve as a promising prognostic indicator in KIRC." (PMID 37790849, 2023). "Generally, TJP1 has been reported to function as a tumor suppressor in many earlier studies." (PMID 37790849, 2023). "Then, the overexpression of circEPS15 suppressed tumor cell invasion and migration by inhibiting the TJP1/CDH2/VIM signaling pathway and retarded cell cycle progression, which was confirmed by the Transwell culture system, wound healing assays, flow cytometry and western blot assays." (PMID 35211158, 2022). "In addition, miR-765 mimics obviously down-regulated the expression of several EMT-related markers (e.g., COL3A1, FN1, CDH2, S100A4, MMP9, SNAIL and ZEB1) and up-regulated TJP1 expression in tumor lesions." (PMID 33859750, 2021). "IL32 was independently and positively associated with Ki67, HIF1A, and ACTA2 and negatively with TJP1 in tumors and with IL10Ra and BCLxL in non-transformed tumor-adjacent tissue." (PMID 33020452, 2020). "Tumor cells secrete miR-105, which targets ZO-1, the tight junction protein-1 in endothelial cells." (PMID 33321819, 2020). "In contrast, zo-1 (TJP1) was overexpressed in the tumor bud samples." (PMID 28687755, 2017). "However, there are also studies suggesting that Tjp1 has tumor suppressive properties." (PMID 38255907, 2024). "In addition, to confirm that HK2 can regulate EMT in CRC, we performed IHC staining to detect TJP1, E‐cadherin, vimentin and Twist1 expression in the tumour tissues of CRC patient samples, and the immunohistochemical staining of these proteins exhibited different degrees of positivity." (PMID 34378321, 2021).
tumor (continued). "It exerts its effects by targeting key tumor suppressors PTEN and TJP1, thereby fostering a pro-tumor microenvironment." (PMID 40764998, 2025). "TJP1 is one of the endothelial markers in the epithelial-mesenchymal transition (EMT) process and involved in tumor proliferation, cell communication, and angiogenesis, but the function of TJP1 in KIRC has not yet been explored." (PMID 37790849, 2023). "The identified potential tumor suppressor genes included DAG1, SLC39A8, TMEM173/STING1, RDX, TJP1, CTNNB1, and SMC3." (PMID 36499305, 2022). "Multiple studies demonstrated that cell junction proteins, such as TJP1 and CDH5, regulated tumor angiogenesis to promote tumor invasion and metastasis." (PMID 35173549, 2022). "Fold change in expression of epithelial marker TJP1 increased along with increasing TNM and the primary tumor extension." (PMID 32630408, 2020). "TJP1 (ZO-1) and TJP2 (ZO-2) proteins were also expressed by the majority of progenitor and stem cells from tumor cell cultures, whereas only a minority of the total cell population expressed PAPPA." (PMID 18492237, 2008). "Accordingly, ODC1 expression correlated positively with TJP1 in both non-cancerous and tumor tissue." (PMID 32630408, 2020). "Because EMT initiation is a critical process in tumour progression, we evaluated the effect of BEST4 on EMT using quantitative polymerase chain reaction (qPCR) and found that BEST4 expression upregulated CDH1 and TJP1 and downregulated VIM and TWIST1 in HCT116 compared with the control (p<0.05)." (PMID 39699952, 2024). "To date, the literature supports the tumor suppressor functions of DAG1, SLC39A8, TMEM173/STING1, TJP1, CTNNB1, and SMC3, but not RDX." (PMID 36499305, 2022).